GSK3B (glycogen synthase kinase 3 beta)
Diseases named in the same sentence as GSK3B in open-access papers (continued):
Sharing a sentence is not in itself a finding about the gene and the disease.
pancreatic cancer (continued). "Notably, pancreatic cancer cell lines characteristically have increased GSK-3β Y216- and decreased S9-phosphorylation, suggesting that GSK-3β is largely in an activated state in PDAC to drive various pro-tumorigenic processes." (PMID 34356465, 2021). "Among GSK-3β inhibitors that are currently tested in clinical trials, 9-ING-41 was selected as it was recently granted fast-track designation for treatment of patients with pancreatic cancer by the U.S. Food and Drug Administration (FDA)." (PMID 34955846, 2021). "Moreover, a combination of GSK-3β inhibitors, such as AR-A014418 and 9-ING-41, with chemotherapeutic drugs had a synergistic effect in killing pancreatic cancer cells in vitro and in vivo in a xenograft model." (PMID 34955846, 2021). "Another study reported that upregulated β-catenin signaling does not affect the survival of pancreatic cancer cells during inhibition of GSK3β." (PMID 32503133, 2020). "In this study, we provide a novel notion that PRMT5 induces the phosphorylation of EGFR, and then activates phosphorylation of Akt and its downstream GSK3β, and thereby up‐regulates expression of β‐catenin to enhance the migratory and invasive motility and promotes EMT of pancreatic cancer cells." (PMID 31851779, 2020). "PANC-1 pancreatic cancer cells have elevated levels of tyrosine (Y)-216-phosphorylated GSK-3β (active form of GSK-3β) than non-neoplastic HEK293 cells." (PMID 32365809, 2020). "To evaluate whether inhibition of PP2A affects the antitumor effect of FUT‐175 and phosphorylated GSK‐3β level, we examined cell viability, GSK‐3 activity and apoptotic signal in the pancreatic cancer cell lines treated by FUT‐175 with PP2A inhibitor." (PMID 29863120, 2018). "The observation that GSK-3β regulates NF-κB function without affecting phosphorylation of P65 and IκBα degradation has been reported in a previous study on pancreatic cancer cells." (PMID 29930281, 2018). "Given that ORI could activate GSK3β activity and up-regulate the expression of DKK1 in human osteosarcoma, the anti–migratory effect of ORI on pancreatic cancer cells might result from targeting Wnt/β–catenin signalling." (PMID 27453691, 2016). "Similar observations were also reported by other investigators, where inhibition of GSK3β in pancreatic cancer cells significantly inhibited NFκB activity but failed to sensitize to gemcitabine." (PMID 27602497, 2016). "A recent study suggested RES induced apoptosis and cell cycle arrest via modulation of ERK1/2 and GSK3β pathways in human pancreatic cancer cell line AsPC1 without phosphorylated STAT3 and NFκB50." (PMID 27539371, 2016). "Furthermore, overexpression of miR-33a in pancreatic cancer cell lines suppressed Pim-3 expression, leading to downregulation of the AKT/Gsk-3β/β-catenin pathway." (PMID 25971209, 2015). "Unexpectedly, the phosphorylation levels of AKT, Erk1/2 and GSK-3β were not all affected by adiponectin in pancreatic cancer cells, which suggested that an unconventional pathway regulates β-catenin." (PMID 25051362, 2014). "We previously found that GSK3β inhibition did not affect endogenous NF-κB transcriptional activity in tumor cells established from pancreatic cancers and glioblastoma." (PMID 24212624, 2011). "Furthermore, in pancreatic cancer cells, the citrus fruit bioactive flavonoid apigenin strongly upregulated IL17F (>100-fold) and induced cell death through inhibition of the glycogen synthase kinase-3β (GSK3β)/nuclear factor kappa B (NFKB) signaling pathway." (PMID 36292624, 2022). "In pancreatic cancer, HNF4α deletion led to a glycolytic energy metabolism transition from typical pancreatic adenocarcinoma to squamous pancreatic cancer, in which Fructose-Bisphosphate Aldolase A (ALDOA), Hexokinase 1 (HK), and Glycogen Synthase Kinase 3 Beta (GSK3β) genes are upregulated." (PMID 36249028, 2022).
pancreatic cancer (continued). "Indeed, inhibition of GSK-3β activity has been shown to trigger apoptosis only in human pancreatic cancer cells but not in human non-transformed pancreatic epithelial cells through JNK pathway." (PMID 24367688, 2013). "In contrast, the effect of the GSK3β inhibitor on NEK2 and PD-L1 expression was not very stable and significant in pancreatic cancer cells." (PMID 34315872, 2021). "In pancreatic cancer, GSK3A but not GSK3B induced constitutive noncanonical NF-kappa-B signaling by stabilizing nuclear p52, although upregulation of GSK3A and GSK3B caused by mutant K-ras resulted in activation of constitutive canonical NF-kappa-B43." (PMID 28630423, 2017). "In these later cell types, GSK3β expression or activation was either not affected by NDRG1 expression in prostate and colon adenocarcinoma cancer cells or downregulated and inactivated by NDRG1 expression in pancreatic cancer cells." (PMID 40378957, 2025).
gastric cancer (147 papers, 2008 to 2026). A primary or metastatic malignant neoplasm involving the stomach. "A previously published study has implicated that CD36 promotes metastatic disease in gastric cancer via the Akt/GSK-3β/β-catenin pathway." (PMID 35008415, 2022). "AQP3 overexpression in human gastric cancer cells is associated with an increase in the level of phosphorylated GSK3β inactive form, resulting in a rise of nuclear β-catenin." (PMID 33924772, 2021). "In summary, this study established that cyclin G2 suppresses Wnt/β-catenin signaling in gastric cancer, acting through association with and impact Dpr1 phosphorylation to stimulate β-catenin degradation in a GSK-3β-dependent manner." (PMID 30547803, 2018). "Mutated phosphoinositide 3-kinase (PI3K) and phosphatase and tensin homolog (PTEN) cause AKT activation and GSK-3β inactivation to induce SHP2-activated cellular unresponsiveness to IFN-γ in human gastric cancer AGS cells." (PMID 26934444, 2016). "High activity of GSK3β was found to be frequently present in early-stage gastric carcinoma and was positively associated with good prognosis." (PMID 25003395, 2014). "The present study was performed to determine the expression status of active form of GSK-3β phosphorylated at Tyr216 (pGSK-3β) and its relationship with other tumor-associated proteins in human gastric cancers." (PMID 20704706, 2010). "Our results demonstrated that activated GSK-3β was more frequent in the early-stage gastric carcinoma, was negatively associated with nodal status, and was positively associated with better prognosis." (PMID 20704706, 2010). "For example, high GSK3β levels are associated with better prognosis in gastric cancer." (PMID 35350242, 2022). "In Cox-2-deficient gastric cancer cells, celecoxib induces caspase-dependent apoptosis via the Akt/GSK3β/NAG-1 pathway; it inhibits Akt phosphorylation, and GSK3β, a downstream target of Akt, and upregulates NAG-1 expression, a pro-apoptotic and anti-tumorigenic protein." (PMID 29904021, 2018). "The findings in this study suggested that AKT/GSK3β signaling pathway might be implicated in the tumor-suppressing function of OPCML in gastric cancer." (PMID 28407749, 2017). "We previously showed that glycogen synthase kinase (GSK)-3β facilitates IFN-γ-activated STAT1 by inhibiting SHP2, and aberrant PI3K and a decrease in PTEN increase AKT activation and GSK-3β inactivation to cause SHP2-activated IFN-γ resistance in gastric cancer AGS cells." (PMID 26934444, 2016). "It has been reported that the pathway blocked by dickkopf WNT signaling pathway inhibitor 1 (DKK-1), naked cuticle homolog 1 (NKD1) and glycogen synthase kinase 3 beta (GSK3β) caused a robust reduction in the activity of wnt/β-catenin signaling and self-renewing capacity of gastric cancer cells." (PMID 27846906, 2016). "Additionally, high activity of GSK3β was found to be frequently present in early-stage gastric carcinoma and was positively associated with good prognosis." (PMID 25003395, 2014). "Knockdown of FBXW2 (sh-FBXW2) promoted gastric cancer cell viability and invasion while increasing β-catenin expression and reducing GSK3β and Axin2 levels." (PMID 40225854, 2025). "The elevation of MGST1 has demonstrated enhanced cell proliferation, migration, invasion of trophoblast by the activation of the PI3K/AKT/mTOR pathway, and activation of the AKT/GSK-3β/β-catenin axis in gastric cancer cells." (PMID 40778224, 2025). "LHPP, a histidine phosphatase, inhibits glycolysis and proliferation in gastric cancer cells by suppressing glycogen synthase kinase 3 beta (GSK3b) phosphorylation and mediating hypoxia‐inducible factor 1 alpha (HIF1A)." (PMID 39802639, 2025). "AKT has been reported to regulate gastric cancer cell migration by modulating GSK3β activity and Snail expression." (PMID 39337655, 2024).
gastric cancer (continued). "Previous research has reported that Erianin also can down-regulated the expression of p-GSK-3β protein, and play a benign role in precancerous lesions of gastric cancer by inhibiting the HRAS-PI3K-AKT signaling pathway." (PMID 39605083, 2024). "YJD (Yin-Ju-Di), a traditional Chinese medicine, is introduced as a potential therapeutic agent that inhibits NRF2 expression through the AKT/GSK3β pathway in gastric cancer." (PMID 38562143, 2024). "Overexpression of MGST1 induces gastric carcinoma cell proliferation by activating the Akt/GSK-3β signaling pathway." (PMID 39711549, 2024). "For example, the Helicobacter Pylori organism activates EMT through the MAPK/ErK-NF -kB pathways and the suppression of GSK3β activity in gastric cancer." (PMID 37051502, 2023). "Previous studies have shown that S9 phosphorylation promotes the growth and migration of gastric cancer cells, whereas constitutive activation of GSK3B correlated to better prognosis of gastric cancer patients." (PMID 36520032, 2023). "A previous report showed that RACK1 interacts with GSK3β and promotes β-catenin degradation in gastric cancer cells." (PMID 37848434, 2023). "CircMAP2K2 regulates the PCBP1/GPX1 axis through proteasome‐mediated degradation, resulting in an epithelial‐to‐mesenchymal transition (EMT)‐like phenotype, and activated AKT/GSK3β signaling pathway enhances proliferation and metastasis of gastric cancer." (PMID 37752765, 2023). "Overexpression of SFRP1 in gastric cancer cells enhance cell growth and migration through Rac and GSK3β dependent mechanisms." (PMID 37091166, 2023). "IC53d promotes gastric cancer cell proliferation and invasive phenotypes via the promotion of GSK3b and Akt phosphorylations, further increasing Cyclin D1 and G1 to S phase transition." (PMID 36769170, 2023). "The knockdown of MICAL2 significantly attenuated migratory ability and β-catenin nuclear translocation in gastric cancer cells while LiCl treatment, an inhibitor of GSK3β, reversed these MICAL2 knockdown-induced effects." (PMID 36064550, 2022). "miR6778-5p promotes the proliferation of Drosha low-expressing gastric cancer cells by targeting GSK3β." (PMID 36210981, 2022). "To clarify the molecular mechanism of miR6778-5p regulating the low expression of Drosha in gastric cancer, we used the miRTarBase and TargetScan databases to find that GSK3β was a potential target gene of miR6778-5p." (PMID 36210981, 2022). "Briefly, LMTK2 silencing can inhibit the proliferation of gastric cancer cells in vitro and tumor growth in vivo by regulating GSK-3β phosphorylation and β-catenin nuclear translocation." (PMID 34719320, 2022). "The involvement of the PI3K/AKT/GSK-3β/β-catenin signaling pathway in EMT in gastric cancer cells has been reported and inhibition of this pathway suppresses EMT." (PMID 35355710, 2022). "In conclusion, LMTK2 silencing can inhibit the proliferation of gastric cancer cells in vitro and tumor growth in vivo by regulating GSK-3β phosphorylation and β-catenin nuclear translocation." (PMID 34719320, 2022). "In this research, we demonstrated that miR6778-5p inhibits the expression of GSK3β via binding the 3′UTR of GSK3β mRNA in gastric cancer cells with Drosha knockdown." (PMID 36210981, 2022). "Mechanistic studies revealed that ACTN1 regulates the epithelial-mesenchymal transition (EMT) and tumorigenesis of gastric cancer via the AKT/GSK3β/β-catenin pathway." (PMID 34546849, 2021). "At last, we also proved that Cos activated prodeath autophagy to induce intrinsic apoptosis via modulation of the AKT/GSK-3β signaling pathway in gastric cancer." (PMID 34869312, 2021). "Meanwhile, TNFRSF11B activated the phosphorylation of GSK-3β and enhanced the expression of β-catenin and its downstream effectors to strengthen the invasiveness of gastric cancer." (PMID 34938284, 2021).
gastric cancer (continued). "Mechanistic studies revealed that ACTN1 regulates the epithelial-mesenchymal transition (EMT) and tumorigenesis of gastric cancer via the AKT/GSK3β/β-catenin pathway, confirmed by the inhibitor of AKT MK2206." (PMID 34546849, 2021). "IGHG1 promoted gastric cancer cell proliferation, invasion and chemo-resistance through up-regulation of β-Catenin level mediated by Akt/GSK-3β phosphorylation." (PMID 34315496, 2021). "In another report, Wnt5a promoted cell migration via the PI3K/AKT/GSK3b/RhoA signaling pathway in gastric cancer." (PMID 34794402, 2021). "One study reported that it suppresses gastric cancer by repressing AKT/GSK3β signaling to inhibit autophagy." (PMID 34869312, 2021). "Previous research has found that AKT/GSK-3β/β-catenin signaling is crucial for the proliferation and invasion of gastric cancer cells." (PMID 34453028, 2021). "The results from our study demonstrated that IGHG1 upregulation in gastric cancer significantly elevated Akt and GSK-3β phosphorylation, which in turn increased β-Catenin level by suppression its degradation caused by phosphorylation." (PMID 34315496, 2021). "Our research further suggested that IGHG1/AKT/GSK-3β/β-Catenin axis acted as novel pathway which regulated gastric cancer cellular malignant behavior." (PMID 34315496, 2021). "DKK-1, 15 μmol/L Wnt/β-catenin signal pathway inhibitor, was added to gastric cancer cells for 48 h to detect cell proliferation and apoptosis, as well as Wnt2, p-GSK-3β, and β-catenin protein expressions." (PMID 32904598, 2020). "Our research systematically assessed the effects of TNFRSF11B in gastric cancer and found the novel regulation of the GSK3β/β-catenin pathway through TNFRSF11B." (PMID 32398963, 2020). "AR-A014418, an ATP-competitive and selective GSK-3β inhibitor, has been reported to suppress the proliferation and induce the apoptosis of gastric cancer, synovial sarcoma, and fibrosarcoma cells in vitro as well as in vivo." (PMID 32526891, 2020). "Previously, we demonstrated that CDK5RAP3 represses AKT phosphorylation, which promotes GSK-3β phosphorylation in gastric cancer." (PMID 31728130, 2019). "• The phosphorylation of GSK3β was significantly suppressed by Reg3A overexpression, whereas, was obviously increased in Reg3A-silenced gastric cancer HGC-27 cells." (PMID 31921694, 2019). "Our study demonstrated that the expression of p-AKT (Ser473) and p-GSK-3β (Ser9) was negatively correlated with CDK5RAP3 in stable gastric cancer cell lines." (PMID 29540196, 2018). "It is possible that STIP1 regulates the Wnt/β-catenin pathway by indirectly affecting the activity of p-GSK-3β in gastric cancer." (PMID 29335007, 2018). "LMO3 has been proved to promote cell invasion or proliferation through Akt-mTOR/GSK3β signaling in gastric cancer." (PMID 30219064, 2018). "Using GSK-3β inhibitors and a GSK-3β-mediated β-catenin phosphorylation site mutation AGS cell line, we revealed that cyclin G2 inhibited gastric cancer proliferation and migration through the Wnt/β-catenin signaling." (PMID 30547803, 2018). "CDK5RAP3 repressed AKT phosphorylation, which promoted GSK-3β phosphorylation, thereby suppressing β-catenin protein expression and, consequently, gastric cancer." (PMID 29540196, 2018). "In neoadjuvant-treated gastric cancer, the expression profiling of stem cell-related genes indicated that Notch2, GSK3β, and β-catenin gene signatures predict survival." (PMID 30470250, 2018). "For example, well-host adapted opportunistic organism, Helicobacter pylori induces EMT through MAPK/Erk-NF-kB signaling pathway and suppresses GSK3β activity by stimulating the PI3K/Akt pathway in gastric cancer." (PMID 29250491, 2017). "This study revealed that AKT and its downstream target GSK3β were constitutively phosphorylated in the two gastric cancer cell lines and their phosphorylation levels were markedly suppressed by ectopic expression of OPCML." (PMID 28407749, 2017).